SLC43A1 (solute carrier family 43 member 1)
Description:
Uniport that mediates the transport of neutral amino acids such as L-leucine, L-isoleucine, L-valine, and L-phenylalanine. The transport activity is sodium ions-independent, electroneutral and mediated by a facilitated diffusion. Mediates the efflux of 3,3'-diiodo-L-thyronine (3,3'-T2) and 3-iodo-L-tyrosine (MIT).
Synonyms: LAT3; PB39; POV1; R00504
Tractability: Antibody: UniProt places it where antibodies can reach, with high confidence; its Gene Ontology location is reachable by antibodies, with high confidence; UniProt predicts a signal peptide or a membrane-spanning region; the Human Protein Atlas places it where antibodies can reach. PROTAC: ubiquitination databases record sites on it; its protein half-life has been measured.
Target class: Transporter; Electrochemical transporter; SLC superfamily of solute carriers; SLC43 family of large neutral amino acid transporters
Gene: Protein-coding gene on chromosome 11 (57,484,064 to 57,515,780, reverse strand). Ensembl gene ENSG00000149150.
Subcellular location: Cell membrane; Apical cell membrane; Endoplasmic reticulum membrane
Subcellular location (Human Protein Atlas): Golgi apparatus; Plasma membrane; Vesicles
Pathways (Reactome):
Transport of small molecules: Amino acid transport across the plasma membrane
Gene Ontology:
Molecular function: L-isoleucine transmembrane transporter activity; L-leucine transmembrane transporter activity; L-valine transmembrane transporter activity; neutral L-amino acid transmembrane transporter activity; protein binding; amino acid transmembrane transporter activity; L-amino acid transmembrane transporter activity; transmembrane transporter activity
Biological process: isoleucine transport; L-leucine transport; L-valine transmembrane transport; negative regulation of amino acid transport; negative regulation of L-leucine import across plasma membrane; neutral amino acid transport; amino acid transport; transmembrane transport
Cellular component: apical plasma membrane; podocyte foot; endoplasmic reticulum membrane; plasma membrane
Genetic constraint (gnomAD): Loss-of-function variants: 30 observed, 59.35 expected, observed/expected ratio (o/e) 0.51, 90% interval 0.38 to 0.69. The upper end of that interval is the gene's LOEUF score, 0.69, which puts it in group 2 of 6, group 1 being the genes least tolerant of losing a copy. Missense variants: 593 observed, 722.22 expected, observed/expected ratio (o/e) 0.82, 90% interval 0.77 to 0.88. Synonymous variants: 259 observed, 296.76 expected, observed/expected ratio (o/e) 0.87, 90% interval 0.79 to 0.97.
Homologues: Orthologues: chimpanzee SLC43A1 (99% identical), macaque SLC43A1 (96% identical), dog SLC43A1 (87% identical), rabbit SLC43A1 (86% identical), mouse Slc43a1 (84% identical), rat Slc43a1 (84% identical), guinea pig SLC43A1 (77% identical), pig SLC43A1 (72% identical), tropical clawed frog slc43a1 (60% identical), zebrafish slc43a1b (60% identical), zebrafish slc43a1a (58% identical). Paralogues in human: SLC43A2 (57% identical).
Diseases named in the same sentence as SLC43A1 in open-access papers:
SLC43A1 is named in the same sentence as 18 diseases in open-access papers, as found by Europe PMC text mining. Sharing a sentence is not in itself a finding about the gene and the disease. The quoted sentences say what the papers report.
prostate carcinoma (7 papers, 2017 to 2025). A carcinoma that arises from epithelial cells of the prostate gland. "SLC6A14 and SLC43A1 are also implicated in leucine transport, with SLC43A1 overexpression correlating with prostate cancer aggressiveness." (PMID 41179661, 2025). "What is known is that some of these gene products were shown to be implicated in prostate cancer progression, such as, for example, SLC7A5, SLC7A11, SLC11A1, SLC43A1 and SLC1A3." (PMID 36831650, 2023). "SLC43A1 or LAT-3 was shown to be overexpressed in androgen receptor-expressing prostate cancer." (PMID 38705513, 2024). "LAT3 (SLC43A1) was first named POV1, “Prostate cancer Overexpressed gene 1”, and it was upregulated in prostate cancer as a gene of unknown function." (PMID 37047148, 2023). "Topics enriched in Samples 4 and 16 include genes such as AR, GRHL2, FOXA1, SLC43A1, WNT7B, which are known downstream players active in prostate cancers with ERG expression." (PMID 34911933, 2021).
colorectal cancer (3 papers, 2023 to 2025). A primary or metastatic malignant neoplasm that affects the colon or rectum. "A case study using ExpOmics identified two potential oncogenes, SERPINE1 and SLC43A1, that may regulate colorectal cancer through distinct biological processes." (PMID 39128019, 2024).
embryonal carcinoma (1 paper, 2022). A non-seminomatous malignant germ cell tumor characterized by the presence of large germ cells with abundant cytoplasm resembling epithelial cells, geographic necrosis, high mitotic activity, and pseudoglandular and pseudopapillary structures formation. "L-type amino acid transporter 3 (LAT3/SLC43A1), a vital transporter the uptake of amino acids, is expressed abundantly in seminoma, which may cause the difference between seminoma and embryonal carcinoma." (PMID 36713456, 2022).
liver cancer (1 paper, 2019). An epithelial or non-epithelial malignant neoplasm that arises from the liver. "TCGA data showed a high level of SLC43A1 expression in both liver and liver cancer with a much tighter range of expression in the liver than in HCC." (PMID 31119488, 2019).
neuroblastoma (1 paper, 2022). Neuroblastoma (NB) is the most common solid, extracranial childhood tumor. "Knockdown of SLC7A5 or SLC43A1 expression in neuroblastoma cells represses the uptake of essential amino acids, as determined by 3H-Leucine transport assay, leading to a significant decrease in the intracellular levels of isoleucine, leucine, phenylalanine, and valine." (PMID 36077650, 2022). "Moreover, SLC7A5 or SLC43A1 depletion reduces MYCN expression by interfering with MYCN mRNA translation and attenuates neuroblastoma cell growth in vitro and in vivo." (PMID 36077650, 2022).
cancer (11 papers, 2016 to 2025). A tumor composed of atypical neoplastic, often pleomorphic cells that invade other tissues. "Of note, our drug sensitivity analysis showed that SLC43A1 overexpression sensitizes cancer cell lines to Nilotinib, Palbociclib (PD0332991), Crizotinib (PF2341066), and γ-secretase inhibitor (L685458)." (PMID 37397501, 2023). "Noteworthy, sar@LIP induced the up-regulation of SLC43A1 (solute carrier family 43, member 1), whose major role is amino acid transport and the supply of nutrients into cancer cells." (PMID 27646588, 2016). "The transcription factor MYC, one of the most frequently amplified genes in human malignancies, is a master-regulator of amino acid metabolism promoting the expression of transporter proteins such as SLC1A5, SLC7A5 and SLC43A1 and thus, driving cancer growth by effective amino acid delivery." (PMID 33401748, 2021). "Most likely, these factors cooperate with MYC to maximize SLC7A5/SLC43A1 (and additional transporters) expression and EAA uptake in human cancers." (PMID 32651356, 2020). "Two other sodium-independent large amino acid transporters, SLC43A1 and SLC43A2 are also absent, leaving SLC6A15 encoding a known transporter of BCAA found in the mammalian brain, and SLC7A6, an antiporter exporting Arg and Lys in exchange for Leu, Ile and Gln also expressed in brain and cancers." (PMID 37918802, 2023).
tumor (9 papers, 2019 to 2025). "Promoters of some genes with functions in amino acid transport (Slc7a11, Slc38a1, and Slc43a1) were occupied by ATF4 in DLD-1 MycER tumor cells." (PMID 40542844, 2025). "MYC up-regulates the expression of solute carrier family 7 member 5 (SLC7A5) and solute carrier family 43 member 1 (SLC43A1), which elevates the uptake of the essential amino acids to promote tumor progression." (PMID 40290126, 2025). "Intriguingly, we found that the high expression of two potential tumor promotor genes (TSNAP1 and SLC43A1) is associated with a better prognosis in PCa." (PMID 32849794, 2020). "In the core ceRNA network, only 3 of 10 RNAs (SNHG3, TSNAP1 and SLC43A1) are up regulated in the tumor tissues, suggesting their potential tumor promotion effect." (PMID 32849794, 2020). "Interestingly, the CG probesets of SLC43A1 were collectively unmethylated in the promoter region for all tumor types." (PMID 37397501, 2023). "Studies have reported that SLC7A5, SLC1A5, SLC3A2, SLC43A1 and SLC43A2 are the major BCAA transporters in tumor cells." (PMID 33882453, 2021). "In BCAA dependent tumor cells, BCAAs are imported into the cell via system L transporters (LAT1/SLC7A5, LAT2/SLC7A8, LAT3/SLC43A1) and the system b(0,+) transporter b(0,+)AT1/SLC7A9." (PMID 34094976, 2021). "Consistent with our analysis findings, the mean expression levels of SLC43A1 and ELOVL6 were significantly lower while HOXC8 was significantly higher in CCA samples than in non-tumor liver samples in the GSE26566 dataset." (PMID 31448221, 2019).
SLC43A1 also shares sentences with these, for which no sentence is quoted: angiosarcoma (1 paper); breast carcinoma (1); diabetes (1); glioma (1); infection (1); influenza (1); leukaemia (1); lymphoma (1); Parkinson disease (1); primary immunodeficiency (1); seminoma (1).